TSG101 (tumor susceptibility 101)
Diseases named in the same sentence as TSG101 in open-access papers (continued):
Sharing a sentence is not in itself a finding about the gene and the disease.
cancer (continued). "Importantly, a number of studies have shown changes in expression of ESCRT components in human cancer cells, including changes in expression of ESCRT-I components Tsg101 and Vps37A and ESCRT-III components Chmp1A and CHMP3." (PMID 23418496, 2013). "Whether loss of TAL expression and functionality contributes to an upregulation of TSG101 in cancer is entirely unclear, and it has not been reported that LRSAM1 mutant mice, which exhibit only a very mild neuropathy phenotype with age, develop any tumors." (PMID 32075127, 2020). "Thus far, it has not been demonstrated that TSG101 levels are dependent on the functionality of MDM2 in cancers that are driven by this bona fide oncogene." (PMID 32075127, 2020). "Currently, there are no reports about the functional roles of TSG101 phosphorylations and the effect of an open (O-MAD2) and a closed (C-MAD2) conformations in MAD2-overexpressing cancer cells." (PMID 39551802, 2024). "sEV enrichment was verified by transmission electron microscopy and western blotting using antibodies against ALIX, TSG101, CD63, CD81, CD9 (sEV markers), and also against GRP94 (negative control), HSP70 (cancer biomarker), and PD-L1." (PMID 37973956, 2024). "However, conclusive results on the absence of Tsg101 and ALIX in non MVB-derived EVs are still lacking, neither is it clearly known whether they can be identified in exosomes from all cell systems, including cancer." (PMID 26861306, 2016).
infection (36 papers, 2011 to 2025). The state of being infected such as from the introduction of a foreign agent such as serum, vaccine, antigenic substance or organism. "The IP results showed a faint band of gB which suggest a direct or indirect association of Tsg101 with KSHV particles during de novo infection (lane 2)." (PMID 27764233, 2016). "Mutation at the L-domain disrupts the TSG101-dependent infection of RABV." (PMID 37042780, 2023). "Since Tsg101 has previously been implicated in budding of arenaviruses, we addressed the effect of the knockdowns on viral entry by blocking secondary infection with 20 mM ammonium chloride added at 4 hours post infection." (PMID 21931550, 2011). "TDEVs were collected 24 h following infection and expression of AliX, TSG101 and CD9 were determined by immunoblot analysis." (PMID 39763667, 2024). "To illustrate the role of ALIX and TSG101 in transporting PEDV or PEAV, we depleted ALIX or TSG101 in Vero cells and visualized cells using transmission electron microscopy 2 h after infection." (PMID 38489378, 2024). "STING degradation triggered by the infection of herpes simplex virus-1 (HSV-1) was also retarded in Tsg101-knockdown primary MEFs." (PMID 36918692, 2023). "The expression of exosomal markers, CD63, HSP70, and TSG101, was much lower after infection with this mutant virus." (PMID 36790212, 2023). "Altogether, these results suggest that both Tsg101 and Atg1 trigger separate membrane repair pathways and restrict M. marinum access to the cytosol during infection." (PMID 30596802, 2018). "Compared to the uninfected cells, KSHV infected cells showed a substantial increase in triple colocalization of KSHV-gB, Tsg101 and dextran molecules that gradually increase during the course of infection (yellow arrows)." (PMID 27764233, 2016). "In immunofluorescence analysis, MARV-infected IQGAP1-depleted cells were characterized by accumulations of nucleocapsids in the cell periphery similar as observed with Tsg101 depletion or rMARVPSAPmut infection (see white arrows)." (PMID 25330247, 2014). "Using several indicator protein‐expressing viruses, in particular the Rluc-expressing PRRSV, we showed that TSG101 was significantly involved in PRRSV infection at the early phase of the infection." (PMID 22355454, 2012). "Infection of these cells with a pBabe-Cre retroviral vector and selection with puromycin led to a substantial downregulation of the Tsg101 protein." (PMID 22479596, 2012). "In contrast, infection with AdV5-EGFP was only mildly affected by depletion of Tsg101 and Vps22, whereas silencing of Hrs and Vps24 enhanced infection." (PMID 21931550, 2011). "To confirm the role of Tsg101 on LASV and LCMV cell entry in a complementary manner, we overexpressed recombinant Tsg101 and assessed the impact on the infection kinetics by ammonium chloride treatment." (PMID 21931550, 2011). "Upon RNAi silencing of the ESCRT proteins Hrs, Tsg101, Vps22, and Vps24, as well as Alix, infection of the α-DG-independent LCMV WE22 was affected to a similar extent as the α-DG-dependent viruses LCMV WE54, LCMV cl-13, and rLCMV-LASVGP." (PMID 21931550, 2011). "We discovered that PEDV or PEAV infection was greatly suppressed in ALIX- or TSG101-depleted cells." (PMID 38489378, 2024). "Subsequent experiments demonstrated that PEAV infection for 30 min could induce co-localization of TSG101 and dextran—macropinocytosis marker." (PMID 38489378, 2024). "Notably, this endosomal sorting function of TSG101 is also critical for the effective infection of DNA tumor viruses, such as human papillomaviruses (HPV) and Kaposi’s sarcoma-associated herpesvirus (KSHV)." (PMID 35269659, 2022). "It was also shown that the loss of ESCRT machinery components TSG101 and VPS4 leads to a reduction in the infection levels of many different PVs, owing to a defect in capsid uncoating, showing that this is an evolutionarily conserved phenomenon in PV infectious entry." (PMID 30181457, 2018).
infection (continued). "Interestingly, we also find a requirement for TSG101 in infection with multiple other PV types, including cutaneous HPV-5 and also the animal-derived MmuPV-1 and SfPV-1." (PMID 28349933, 2017). "Tsg101 knockdown blocking the viral transition from early to late endosomal stages adds a new dimension to the current understanding of host cellular transport proteins involved in KSHV entry and infection, and suggest that Tsg101 can serve as a potential target to control KSHV infection." (PMID 27764233, 2016). "KSHV infection increased the association of Tsg101 with the early endosomes, and the infection did not increase the total level of Rab5 protein." (PMID 27764233, 2016). "Although Tsg101 has previously been implicated in budding of arenaviruses, this was not a concern in our experimental setup, as VSV pseudotypes are replication-deficient, preventing secondary infection." (PMID 21931550, 2011). "Therefore, to confirm that the increase in ubiquitination observed during infection of the tsg101- mutant was due to MCV damage and bacteria access to the host cytosol, and not to failed endocytic cargo sorting, we monitored the colocalization of bacteria with GFP-tagged perilipin (Plin)." (PMID 30596802, 2018). "Our analysis demonstrates that Tsg101 interacts with both upstream complex Hrs and with downstream complex proteins, EAP45 (ESCRT-II), CHMP6 (ESCRT-III) and CHMP5 (ESCRT-III), and CHMP5 and CHMP6 proteins associate with KSHV (glycoprotein gB) particles early during infection." (PMID 27764233, 2016). "TSG101, VPS28, MVB12A, and CHMP6 were knocked down individually in 293T cells, followed by infection of the cells with replication-competent HCoV-OC43." (PMID 40407327, 2025). "Taken together, these results, including the analysis of infections in VPS28 and TSG101 knockdowns, affirm the conclusion that the engagement of ALIX, but not the TSG101 or VPS28 (members of the ESCRT I complex), is required for the scission of LdLPVs." (PMID 40956840, 2025). "Expression of specific protein markers such as TMPRSS2, ACE2, Alix, TSG101, CDs, TLRs, TNF-α, and others were altered in infection-derived EVs when compared to control-derived EVs after FCoV infection." (PMID 39091390, 2024). "The results showed that 30 min after infection, PEAV and Dextran were significantly co-localized with each other and with TSG101." (PMID 38489378, 2024). "As expected, we observed the localization of ALIX and TSG101 in the endoplasmic reticulum or double-membrane vesicle structure after PEDV and PEAV infection." (PMID 38489378, 2024). "As expected, the dsRNA or N protein induced by PEDV or PEAV infection was significantly co-localized with endogenous ALIX and TSG101." (PMID 38489378, 2024). "Dengue virus and JEV were also found to exploit only TSG101, CHMP2/3, and CHMP4 family members in the ESCRT system for infection through systematic siRNA screening." (PMID 35080428, 2022). "We show that during infection of Dictyostelium discoideum with Mycobacterium marinum, the ESCRT-I component Tsg101, the ESCRT-III protein Snf7/Chmp4/Vps32 and the AAA-ATPase Vps4 are recruited to sites of damage at the Mycobacterium-containing vacuole." (PMID 30596802, 2018). "However, it is not known whether the loss of infection is due to TSG101 and VPS4-dependent endosomal perturbation, or whether it has a direct role in sorting of the L2/vDNA viral cargo." (PMID 30181457, 2018). "In the present study, we evaluated the role of Tsg101 in the macropinocytic entry of KSHV and infection." (PMID 27764233, 2016). "The fate of the virus and further studies are needed to fully elucidate the role of Tsg101 and other ESCRT complex proteins during KSHV entry and productive infection." (PMID 27854239, 2016). "Depletion of Hrs, Tsg101, Vps22, and Vps24 in HEK293 affected infection with rLCMV-LASVGP and LCMV in a similar manner as observed in A549 cells (data not shown)." (PMID 21931550, 2011).
infection (continued). "However, silencing of TSG101, CHMP3, VPS4B, or ALIX—components of the ESCRT pathway that control MVB biogenesis—has been shown to impair the infection and entry of CCHFV, indicating that ESCRT plays a role in CCHFV entry." (PMID 40996032, 2025). "Approximately 15% to 19% of LdLPVs displayed TSG101-GFP at 24, 48 and 72 hours after infection." (PMID 40956840, 2025). "FCoV-infected CRFK-derived EVs presented significantly elevated expression of Alix (∗∗p ≤ 0.01), TSG101 (∗∗∗p ≤ 0.001), and CD63 (∗∗p ≤ 0.01) at 48 h infection and significantly increased expression of TSG101 (∗p ≤ 0.05) at 72 h infection relative to the control EVs, respectively." (PMID 39091390, 2024). "PEDV and PEAV infection did not significantly upregulate or downregulate endogenous ALIX or TSG101 expression." (PMID 38489378, 2024). "Results show that infection by two porcine alphacoronaviruses, including porcine epidemic diarrhea virus (PEDV) and porcine enteric alphacoronavirus (PEAV), is dramatically decreased in ALIX- or TSG101-depleted cells." (PMID 38489378, 2024). "The RGNNV infection significantly increased the formation of exosomes, and subsequently, the expression of exosome-related proteins, including ALIX, CD63, Nedd4, and TSG101, was increased as well." (PMID 39494909, 2024). "Given the expression levels of ICP4, a viral protein produced immediately after infection, Tsg101 knockdown did not interfere with the infection of HSV-1." (PMID 36918692, 2023). "TSG101, as a novel host factor interacting with PRRSV N protein, is beneficial to PRRSV virion formation rather than attachment, internalization, RNA replication, and N protein translation during infection." (PMID 35080428, 2022). "There was some variation in the peak of infection between the cell lines; this variation, however, appears to be unrelated to Tsg101, because the KI Jurkat lines were not impaired for particle release, which is the Tsg101-dependent step of HIV-1 replication." (PMID 31519756, 2019). "A recent paper showed that HSV-1 triggered the release of CD63 positive EVs but not alter the exocytosis of TSG101 or Alix, suggesting the infection triggers ESCRT-independent pathways for the release of EVs." (PMID 31068945, 2019). "Another recent finding revealed the role of ESCRT-I protein Tsg101 in KSHV trafficking and transition from early to late endosomes, thus defining novel roles of host proteins that are involved during viral entry and infection." (PMID 27854239, 2016). "Collectively, our studies reveal that Tsg101 plays a role in the trafficking of macropinocytosed KSHV in the endothelial cells which is essential for the successful viral genome delivery into the nucleus, viral gene expression and infection." (PMID 27764233, 2016). "Similar infection rates were observed in all samples, confirming that depleting Hrs or Tsg101 has no impact on bacterial entry." (PMID 27774439, 2016). "A recent study reported that Tsg101 plays an important role during Crimean-Congo hemorrhagic fever virus (CCHFV) entry via the multi-vesicular body (MVB) pathway into host cells, and silencing Tsg101 and other ESCRT components prevented CCHFV infection." (PMID 27764233, 2016). "IFA analysis revealed a substantial increase in Tsg101 localization in Rab7 positive endosomes of HMVEC-d cells during KSHV infection in a time dependent manner, and the levels of Rab7 protein remained the same during infection." (PMID 27764233, 2016). "To further investigate whether MVB biogenesis is critical for CCHFV infection, we tested the effect of depleting cellular Tsg101, Vps24 (ESCRT-III component), Vps4B, and Alix/Aip1 on efficiency of CCHFV-mKate2 infection." (PMID 25233119, 2014). "In cells depleted of Tsg101, Hrs, or Rab7, we observed diminished co-localization between Mtb and LAMP1 and a concomitant increase in co-localization of Mtb with TfR compared to control cells 24 hours post-infection (hpi), suggesting decreased Mtb delivery to degradative compartments." (PMID 24204276, 2013).
infection (continued). "The presence of TSG101 and Alix, complexed with the NS3 protein, on the membranes of cells infected with some flaviviruses has been found to be necessary for viral release, while TSG101 translocation is also a repair mechanism for the plasma membrane, which could be damaged as a result of infection." (PMID 38247836, 2024). "Clear enrichment of TSG101 and PDCD6 was observed in the human foreskin fibroblast infection eluates from 3×HA-GRA64 samples, but not in the untagged control eluates." (PMID 35730903, 2022). "We showed that silencing of essential proteins of the ESCRT-0 (Hrs), -I (Tsg101), and -III (Chmp4B) machineries had no impact on primary infection, nor on the progeny collected." (PMID 27774439, 2016). "Depletion of Hrs, Tsg101, Vps22, and Vps24 under our experimental conditions markedly reduced cell entry of LASV and LCMV, but only mildly affected infection with AdV5 and did not affect early endosomal trafficking of TfR1, excluding general perturbation of membrane trafficking and/or endocytosis." (PMID 21931550, 2011). "Although RNA replication of HCV-JFH1 was not affected in the TSG101 knockdown or the Alix knockdown cells, the infectivity of HCV in the culture supernatants was significantly suppressed in these knockdown cells after HCV-JFH1 infection." (PMID 21264300, 2011). "Importantly, in cells lacking Tsg101, GFP-Vps32 structures were significantly reduced at early times of infection, which may indicate that M. marinum-induced damage triggers one or more pathways of ESCRT-III recruitment to the MCV." (PMID 30596802, 2018).
neurodegenerative disease (3 papers, 2012 to 2025). A disorder of the central nervous system characterized by gradual and progressive loss of neural tissue and neurologic function. "TSG101-dependent trafficking has been implicated in the propagation and spread of misfolded proteins associated with neurodegenerative diseases." (PMID 40563427, 2025). "It has been proposed recently that the various ESCRT complexes including Tsg101 are required for the autophagic degradation of certain protein aggregates that are associated with neurodegenerative diseases." (PMID 22479596, 2012).
peripheral neuropathy (3 papers, 2025). A disorder affecting the peripheral nervous system. "We have also demonstrated that deleting Tsg101 from Schwann cells in the mouse peripheral nervous system resulted in severe, rapid onset peripheral neuropathy associated with “onion bulb” formations and de- or dysmyelination." (PMID 40563427, 2025).
brain diseases (1 paper, 2021). "Tumor susceptibility gene 101 (Tsg101), superoxide dismutase‐2 and Mahogunin‐1, which have been implicated in vacuolating brain diseases including genetic spongiform encephalopathies, were unchanged." (PMID 34291577, 2021).
TSG101 also shares sentences with these, for which no sentence is quoted: gastrointestinal tumors (3 papers); head and neck cancer (2); adenocarcinoma (1); diabetes (1); Down syndrome (1); Ebola (1); head and neck squamous cell carcinoma (1); Hermansky-Pudlak syndrome (1); Hernia (1); Krabbe disease (1); liver cancer (1); lysosomal storage disease (1); membranous nephropathy (1); motor neuron diseases (1); neuropathy (1); pituitary adenoma (1); prostate adenocarcinoma (1); renal carcinoma (1); renal fibrosis (1); soft tissue sarcoma (1); Stroke (1); uterine carcinoma (1); uveal melanoma (1).